TLR2 (toll like receptor 2)
Diseases named in the same sentence as TLR2 in open-access papers (continued):
Sharing a sentence is not in itself a finding about the gene and the disease.
infection (continued). "A robust core pattern of gene expression was observed upon infection with both MAB-S and MAB-R variants compatible with a TLR2 initiated signaling cascade, leading to the activation of nuclear factor kappa B (NF-kB) and resulting in a pro-inflammatory cytokine response." (PMID 26654095, 2015). "Lack of TLR2 strongly impaired cytokine production by cDCs in the very early phase (i.e. 2.5 h post infection), whereas this phase appeared normal in Unc93b1-deficient cells." (PMID 25756897, 2015). "Like what was observed for TLR6, TLR2 was found to be up-regulated by PBMC on day 3 post-infection." (PMID 26226614, 2015). "As NFκB signaling is markedly down-regulated in the late phases of HCMV lytic infection, it is conceivable that the late down-regulation of TLR2 by miR-UL112-3p might contribute to keep the survival/apoptosis balance toward survival." (PMID 25955717, 2015). "This could also be true in our infection model, since it has been demonstrated that cell wall components of P. brasiliensis are recognized by pattern recognition receptors such as TLR2, TLR4 and dectin-1." (PMID 26512987, 2015). "However, similar to fibroblasts, TB40E infection resulted in the progressive down-regulation of TLR2 at 4-6dpi that temporally correlated with the progressive accumulation of miR-UL112-3p in TB40E-infected cells." (PMID 25955717, 2015). "Moreover, infection of a human cell line with L. interrogans was shown to induce TLR2-dependent production of fibronectin, a component of the extracellular matrix." (PMID 24498450, 2014). "A plausible explanation is that CR3, TLR4, and TLR2, which are segregated in resting macrophages, are recruited to a single signaling platform, by as yet unknown factors, on infection with L. major." (PMID 24732131, 2014). "TLR2 contributes to the inflammatory response and control of infection in mouse models of meningitis and pneumonia and has additional effects that may affect disease development." (PMID 25172490, 2014). "L. plantarum has previously been shown to modulate TLR2 expression which may play a role in modifying infection response." (PMID 25127240, 2014). "Upon infection, the host recognizes the pathogen-associated molecular patterns (PAMPs) of viral products via pathogen recognition receptor (PRR) proteins, such as toll-like receptor 2 (TLR2)." (PMID 24795862, 2014). "Inconsistency in the involvement of TLR2/4 in these models could be attributed to different infection regimens or the parasite strain/clones used." (PMID 25157202, 2014). "The ability of TLR2 KO mice to survive a lethal LVS secondary challenge suggested that these mice mount a robust adaptive immune response since T-cells are required for survival during a secondary infection." (PMID 25250027, 2014). "Masking of TLR2-active Lpp by capsular polysaccharides could result in ineffective immune recognition and, thus, facilitate invasive infection." (PMID 24810614, 2014). "Infection with cagPAI– strain 8822 caused a similar reduction in TLR2 expression, suggesting that neither T4SS nor cagPAI is necessary for this H. pylori activity." (PMID 23755130, 2014). "B6 and TLR2 KO mice had similar peak lung bacterial burdens on day 3 post-inoculation indicating that the delayed clearance was not simply due to an initial increase in bacterial burdens that persists during the course of infection." (PMID 25250027, 2014). "However, in TLR2−/− mice H. polygyrus showed reduced egg output by day 28 post infection, compared with wild-type C57BL/6 controls, although considerable variability in egg output was seen in these mice." (PMID 25114104, 2014). "TLR2 is one of the primary pattern recognition receptors involved in recognition of Gram-positive bacteria and has been demonstrated to have divergent signaling pathways that contribute to either the establishment of commensalism or infection." (PMID 25209732, 2014).
infection (continued). "infection with subtypes that bring about dysregulation of TLR-2 signaling, this effect on host cells may be an alternative mechanism driving previously observed Blastocystis-induced epithelial barrier compromise." (PMID 24551212, 2014). "Live whole TIGR4 WT bacteria stimulated a strong TLR2-dependent signal, whereas live Δlgt bacteria did not cause any significant response even with high multiplicities of infection (MOI)." (PMID 25172490, 2014). "High concentrations of chitin particles generated during pathogen invasion and infection may promote inflammation through dectin-1 and TLR2 signalling." (PMID 24722226, 2014). "In MHCII+CD11chigh cells, an increased of TLR2 expression was noted, reinforcing the hypothesis that TLR2 plays a role in these cells during infection." (PMID 23650544, 2013). "The differential use of TLR2 and TLR9 by the immune cells during the acute phase of the infection explains why TLR9- but not TLR2-deficient mice are susceptible to T. cruzi infection." (PMID 23650544, 2013). "The transcription of tlr2 in CD11c+ cells was significantly elevated at 6 weeks post-infection." (PMID 24376539, 2013). "In macrophages (a key effector cell for infection-induced preterm labor), suppression of inflammation by SP-A is not due to sequestration of stimulating ligand by SP-A, is accompanied by decreased degradation of IκBα, and is TLR2 dependent." (PMID 23700442, 2013). "HMGB1 has been suggested as a ligand for TLR2 in signaling following infection with different poxviruses as it is released during cell death and many attenuated strains of vaccinia virus cause widespread cell death, having lost molecules which inhibit apoptosis in the parent strain." (PMID 23844129, 2013). "However, it is important to note that a TLR2 priming-based mechanism need not only be of significance during infection with a single viral pathogen." (PMID 23853595, 2013). "For instance, infection with Mycobacterium bovis BCG induces toll-like receptor 2 (TLR2)-mediated formation of LBs in macrophages while the chemokines eotaxin-1 and RANTES, acting via CCR3 receptors, stimulate LB formation in eosinophils as demonstrated by fluorescence microscopy." (PMID 23555714, 2013). "A larger study with longer supplementation and follow-up periods, allowing monitoring for rates infection or inflammatory conditions, may have permitted analysis of the potential clinical relevance of the demonstrated increase in expression of TLR2." (PMID 23875738, 2013). "Therefore, we analyzed the expression of TLR15, TLR1 and TLR2 genes after infection of HD11 macrophages with live Mycoplasma synoviae for 1, 6 or 24 h." (PMID 24134665, 2013). "In addition, mutants lacking FLT_0325 also induce higher levels of caspase-1 activation dependent on Aim2 and Tlr2 and secretion of IL-1β dependent on Tlr2, Aim2, and Nlrp3 in the early periods of infection." (PMID 24324933, 2013). "Moreover, mice deficient of or with modified versions of TLR2, TIRAP, MyD88 and/or IRAK4 were more susceptible to infection with Staph. aureus, En. faecium and/or Strep. pneumoniae infection." (PMID 23873783, 2013). "In vivo, the deficiency or absence of TLR2 causes lower levels of inflammatory mediators, but the course of infection does not differ compared with naïve animals." (PMID 23781508, 2013). "Uncommonly, TLR2 possesses a dual role during the infection." (PMID 23650544, 2013). "In fact, mice infected with very high doses of both S. suis ST1 and ST7 (≥ 1×108 CFU/mL) died within 72 h of infection indicating that although TLR2 seems to play an important role, in vivo activation of host cells by S. suis would require a multimodal recognition system (results not shown)." (PMID 23724118, 2013). "While this is a small, pilot study, we have shown for the first time in humans that optimal vitamin D levels after supplementation may improve the expression of TLR2 and hence the body’s ability to fight infections." (PMID 23875738, 2013).
infection (continued). "Interestingly, we found that blocking the TLR2-mediated signaling pathway prior to infection restored the phenotype of the ΔkstD mutant in resting MØ to a level similar to that of the wild-type strain." (PMID 23425360, 2013). "The Mtb mutant ∆kstD strain, which is unable to use cholesterol as a source of carbon and energy, has a limited ability to multiply in resting MØ following infection, reflecting a failure of the ∆kstD strain to inhibit the TLR2-dependent bactericidal activity of resting MØ." (PMID 23425360, 2013). "The importance of TLRs during T. cruzi immune response was initially evidenced by studies performed with professional antigen-presenting cells, in which the authors remark the importance of TLR2 as a mediator of the defense mechanisms during the early stages of the host response to infection." (PMID 21869919, 2012). "pDCs do not express TLR2 or 4, however, our results suggest that the absence of TLR2 influences pDC recruitment, potentially through the loss of control of infection that enhances inflammatory responses." (PMID 22724018, 2012). "However, studies with A549 cells have demonstrated the presence and up-regulation of TLR-2 and -4 responses to infection with Klebsiella pneumoniae." (PMID 23024786, 2012). "Infection studies using inbred strains have allowed identification of specific immune mediators that affect host clearance, such as Toll-like receptor 2 (TLR2), MyD88, CD14, IL-10, the chemokine KC, and the production of antibodies against critical B. burgdorferi antigens." (PMID 22110528, 2012). "This suggests an immunoregulatory role for TLR2 during the infection, maybe due to the action of TLR2 ligands on Tregs." (PMID 22496959, 2012). "Taken together these results show that the absence of TLR2 promotes reduced early and increased later DC responses that are associated with increased severity of Chlamydia respiratory disease and infection in early life." (PMID 22724018, 2012). "L. braziliensis-infected TLR2-deficient DCs were more competent in priming naïve CD4 T cells in vitro, correlating with increased IFN-γ production in vivo and enhanced resistance to infection." (PMID 22523644, 2012). "Infection in TLR2/4−/− mice was similar to that in TLR2−/− mice." (PMID 22724018, 2012). "Moreover, recent clinical studies have shown the association of TLR2 and TLR5 gene polymorphisms with susceptibility to infection with M. tuberculosis and L. pneumophila, respectively." (PMID 22367599, 2012). "In airway cells, the TLR2-dependent Ca2+ influx mechanism is induced by the phosphorylation of tyr-616 and -761 in the cytoplasmic tail of TLR2, and these results were confirmed in Staphylococcus aureus-treated cells early in infection." (PMID 23209344, 2012). "Moreover, TLR2 expression is induced by LPS and it has been recently proposed that up-regulation of TLR2 by low levels of bacterial products can contribute to the mechanisms by which the immune system increases its response to an infection." (PMID 22558381, 2012). "Collectively, our results and other studies suggest that TLR2 agonists may have beneficial roles in enhancing host immunity and the clearance of infection." (PMID 22724018, 2012). "Relative to M. bovis BCG-stimulated CD4+ cells treated with scrambled siRNA, transfection of CD4+ cells with TLR2 siRNA prior to M. bovis BCG stimulation decreased infection with R5 virus from 6.2±0.7% to 3.6±1.0% (p = 0.005), and with X4 virus from 10.7±0.8% to 7.0±1.0% (p = 0.001; data not shown)." (PMID 22844428, 2012). "With this prospective hypothesis, TLR2 was found to be significantly differentially expressed in the interaction between gender and day of infection from pre-infection to 3-days post, and from 3-days post to 6-days post." (PMID 23241283, 2012).
infection (continued). "Noticeably, other authors showed that infected TLR2(−/−) mice produced enhanced levels of cytokines suggesting that, in vivo, TLR2 may have a predominant immunoregulatory role during acute infection with T. cruzi parasites, at least with the Y strain." (PMID 21869919, 2012). "This suggests that in some situations involving infections, TLR2 may have anti-inflammatory effects." (PMID 22724018, 2012). "Critically the absence of TLR2 in neutrophils abrogated their phagocytic capacity, which provides a mechanism for loss of control of infection and subsequent enhanced inflammatory responses." (PMID 22724018, 2012). "The role of PRRs, including TLR2, during these infections is thus of particular interest." (PMID 23316483, 2012). "IFNγ levels were significantly reduced in all infected TLR−/− strains, most significantly in TLR2−/− mice, and may have contributed to enhanced infection in TLR2−/− pups." (PMID 22724018, 2012). "Because both TLR4 and TLR2 are recruited to the infection sites during C. parvum infection of H69 cells in vitro, we cannot exclude the possibility that TLR2 also may be involved in C. parvum-induced iNOS mRNA stabilization in biliary epithelial cells." (PMID 22615562, 2012). "Only infection of TLR2 expressing cells resulted in increased IL-8 secretion." (PMID 23061052, 2012). "Similarly, microarray-based analysis of the murine bone marrow-derived macrophage transcriptome following infection with virulent M. tuberculosis in vitro was also shown to induce MyD88-independent signalling pathways, possibly involving TLR2." (PMID 22384131, 2012). "Similarly, the CFUs in the spleen at days 7 and 14 post-infection, as well as in the bone marrow at day 7 post-infection, were significantly higher in TLR2−/− than in control mice." (PMID 21935459, 2011). "Additionally, we show that TLR2 contributes to inflammasome activation in response to infection by L. monocytogenes, a cytosolic bacterium that is also recognized by AIM2." (PMID 21698237, 2011). "As expected, infection of BMDM with C. pneumoniae degraded IκB in wild type but not in TLR2/4 double-deficient cells." (PMID 22096480, 2011). "This in vivo expansion of LKS cells in TLR2−/− mice was delayed until day 7 post- infection." (PMID 21935459, 2011). "In addition, miR-146a and miR-125a-3p/5p were regulated at transcriptional levels upon infection, and miR-125a-3p/5p were found to be TLR2 responsive." (PMID 22114673, 2011). "It would be interesting to test whether TLR2 contributes to cell death during infection with these strains as well." (PMID 21698237, 2011). "Measles virus (MV) is another infection in which TLR2 signaling may have both favorable and unfavorable effects." (PMID 21994762, 2011). "The delayed cell death phenotype was observed in TLR2−/− macrophages up to 10 h post-infection." (PMID 21698237, 2011). "High level IL-12p40 production in ΔROP16 infection was dependent on the host cell adaptor molecule MyD88, but surprisingly was independent of any previously recognized T. gondii triggered pathway linking to MyD88 (TLR2, TLR4, TLR9, TLR11, IL-1ß and IL-18)." (PMID 21931552, 2011). "However, pre-infection challenge with Pam3Cys clearly altered the TLR2 response to S. aureus intraocular challenge, diminishing inflammation, reducing bacterial load, and preserving retinal function in this model." (PMID 22163046, 2011). "Unexpectedly, TLR2/4 double-deficient but not TLR2-deficient mice displayed upon infection with the microorganism significantly higher pulmonary levels of IFNγ than wild type mice." (PMID 22096480, 2011). "We could detect processed caspase-1 at 7.5 h post-infection in TLR2−/− macrophages, but the level was still less than that observed in wild-type macrophages." (PMID 21698237, 2011).
infection (continued). "The cecum from TLR4−/− and MyD88−/− had marked inflammatory cell infiltrates with oedema and epithelial disruption on days 3 and 7 post infection, that was significantly (p<0.05−0.01) greater than the mild inflammation in the cecum of infected wild-type, TLR2−/− or TRIF−/− mice." (PMID 21738466, 2011). "Therefore, TLR2 recognizes a myriad of unrelated molecules, and their role in infection by Leishmania has been evaluated but is still controversial." (PMID 22140456, 2011). "Early mediation of the TLR2 pathway activated at the time of infection may potentially limit TLR2 signaling, unnecessary inflammation, and further damage." (PMID 22163046, 2011). "Furthermore, TLR2−/− animals show an impaired resistance to infection in the lower respiratory tracts." (PMID 20505832, 2010). "We therefore investigated whether MHV-68 could induce the activation of TLR2 transcription during an acute infection in a living animal model." (PMID 21060793, 2010). "Furthermore, the number of CD4−CD8α− DCs per spleen was unchanged upon infection in wild type and MyD88−/− mice, but was significantly increased in TLR2−/−xTLR4−/− and TRIF−/− mice." (PMID 21124820, 2010). "Notable, AdVαT2ib infection reduced surface TLR2 expression to almost baseline levels." (PMID 20388199, 2010). "Some of the type I IFN-inducible mediators such as IP-10 and NO, herein shown to be induced in response to TLR2 activation play an important role not only in the activation and recruitment of inflammatory cells to sites of infection but also have direct anti-microbial effects." (PMID 20422028, 2010). "In addition, lipoproteins from pathogenic bacteria are known inducer of immune responses during infection, generally through interaction with TLR2." (PMID 20927194, 2010). "Similarly, other bacterial pathogens, such as Borrelia burgdorferi, Streptococcus pneumoniae and Mycobacteria BCG, are recognized by TLR2, resulting in clearance of infection in lungs." (PMID 20505832, 2010). "To assess the role of TLR2 signals in pathogenic effector T cells and in Treg we used the T-cell transfer model of IBD 37, whereas IBD models based on infection with the intestinal bacterium Helicobacter hepaticus allowed us to examine the role of TLR2 in innate immune-mediated IBD." (PMID 19950179, 2010). "Our results also suggest that TLR2 is not the sole MyD88-dependent receptor implicated in the antiviral response against the virus since MyD88−/− mice were highly susceptible to infection." (PMID 21060793, 2010). "Notably, the pre-treatment previous to infection with Pam3CSK4, TLR2-agonist, induced a significant reduction of transaminase activity levels and inflammatory foci number in livers of infected B6 mice." (PMID 21072226, 2010). "We hypothesize that AM and other innate immune cells recognize viable M. pulmonis through TLR2-dependent mechanisms, and that this recognition augments the host's cytokine response and their ability to resist infection." (PMID 20505832, 2010). "Importantly, TLR2−/− mice were impaired in their ability to control viral replication in the lungs after five days of infection, suggesting that an effective response against MHV-68 is regulated through this cell membrane receptor." (PMID 21060793, 2010). "Since TLR2-mediated responses may occur early in the host response to infection, any factors that negatively impact TLR2 expression or signaling might influence disease outcomes." (PMID 19835594, 2009). "In LMMs with untransformed TLR variables as the response, the predicted reductions in TNF-α production in mice in the highest louse infection category in relation to mice uninfected with lice were 49% for TLR2/HKLM, 55% for TLR2/zymosan, 59% for TLR9 and 56% for TIR." (PMID 19386086, 2009). "Moreover, total lung inflammation scores, determined from lung tissue slides prepared 24 and 48 h after infection with S. pneumoniae D39, were similar in WT and TLR2 KO mice." (PMID 17711480, 2008).